CRP (C-reactive protein)
Diseases named in the same sentence as CRP in open-access papers (continued):
Sharing a sentence is not in itself a finding about the gene and the disease.
leukocytosis (continued). "Laboratory tests revealed leukocytosis, acute kidney injury of probable prerenal etiology, electrolyte disturbances (hyponatremia and hyperkalemia), and elevated C-reactive protein." (PMID 41567909, 2025). "Biological tests indicated leukocytosis with a white blood cell count of 21.250/mm3, elevated C-reactive protein (CRP) levels at 233 mg/L, and a markedly high procalcitonin value of 23 ng/ml." (PMID 39958682, 2025). "The following preoperative risk factors were identified as being of key significance: an ASA classification of ≥3, elevated CRP levels (≥20 mg/L), and leukocytosis (WBC ≥ 15,000/μL)." (PMID 41375749, 2025). "The patient met two mandatory and two minor criteria (elevated CRP level, neutrophilic infiltration in the skin confirmed by biopsy, and leukocytosis)." (PMID 40718535, 2025). "The laboratory assessment found leukocytosis with neutrophil predominance at 16,000/ml; C-reactive protein (CRP) at 105 mg/l; and hyponatremia at 128 mmol/l was also noted." (PMID 41158889, 2025). "Laboratory tests showed slight leukocytosis (13.08 × 109/L) and elevated C-reactive protein (159.9 mg/L)." (PMID 40062037, 2025). "Laboratory tests can reveal signs of inflammation, such as leukocytosis, elevated CRP levels, acute-phase protein concentrations, and chronic disease anemia." (PMID 40718535, 2025). "Biomarkers of inflammation, particularly leukocytosis, were evident in 40% of patients, while markers such as increased CRP and lactate were less commonly observed." (PMID 40002490, 2025). "Initial laboratory tests at an outside hospital revealed leukocytosis, markedly elevated C-reactive protein (CRP), and computed tomography (CT) evidence of small bowel wall thickening." (PMID 41146753, 2025). "Laboratory evaluation revealed marked leukocytosis (13,000/μL) with neutrophilia (88.6%) and elevated CRP (3.55 mg/dL)." (PMID 41450394, 2025). "PROMs and high CRP values increased the risk of composite outcome 5 by 14% (95%CI: 1.07–1.78, p < 0.001), PROM and leukocytosis by 11% (95%CI: 1.02–1.59, p = 0.001), and PROMs and high PCT values by 21% (95%CI: 1.04–2.10, p < 0.001)." (PMID 39857097, 2025). "The laboratory findings revealed leukopenia, leukocytosis, lymphopenia, lymphocytosis, and elevated C-reactive protein (CRP) levels." (PMID 39998062, 2025). "Blood workup revealed anemia and mild leukocytosis with neutrophilia, as well as elevated serum creatinine (sCr) and markedly increased C-reactive protein (CRP)." (PMID 41510480, 2025). "Our patient also exhibited leukocytosis and elevated CRP levels, findings that were consistent with a majority of the case reports and retrospective studies on appendiceal diverticulitis." (PMID 40136596, 2025). "Laboratory tests revealed leukocytosis, with a white blood cell count of 11,760/μL and an elevated C-reactive protein (CRP) level of 18.3 mg/dL." (PMID 41367003, 2025). "Laboratory data on admission (operative day) demonstrated marked neutrophil-predominant leukocytosis, elevated CRP, and hyperglycemia, indicating systemic inflammation and impaired glucose tolerance." (PMID 41246630, 2025). "Laboratory tests revealed leukocytosis with neutrophil predominance, elevated C-reactive protein (CRP), hyperglycemia, and elevated hemoglobin A1c (HbA1c)." (PMID 40821179, 2025). "Laboratory findings, such as leukocytosis, anemia, and elevated levels of C-reactive protein (CRP) and erythrocyte sedimentation rate (ESR), were the rule; abnormal liver function tests (LFTs) were also frequent." (PMID 40843703, 2025). "Initial laboratory findings revealed leukocytosis (20,000/μL) with neutrophilia (91%), an elevated C-reactive protein (CRP) level of 111 mg/L, and thrombocytopenia (93,000/μL)." (PMID 40255710, 2025). "Laboratory findings showed a decrease in leukocytosis (from 45.4×109/L to 31.9×109/L) and improvement in CRP (from 239 mg/L to 133 mg/L), while renal function remained stable." (PMID 41141097, 2025).
leukocytosis (continued). "During follow-up, mild leukocytosis and elevated CRP levels normalized, likely reflecting the treatment course of transient urinary tract infections." (PMID 39944429, 2025). "Similar to other ruptured VAPAs, reported ruptured ileocolic artery pseudoaneurysms showed leukocytosis and elevated CRP levels." (PMID 40731941, 2025). "Early blood work was notable for leukocytosis, raised CRP, mild hypoalbuminemia, prerenal AKI, and trace proteinuria." (PMID 41018982, 2025). "Despite the presence of elevated CRP (56.09 ± 14.68) and leukocytosis (11.85 ± 4.57), we believe that the significance of laboratory parameters to the diagnosis of MP is limited because these tests are imprecise." (PMID 41137346, 2025). "Imaging confirmed soft tissue edema without abscess formation, and laboratory studies revealed marked leukocytosis, thrombocytosis, hypo-osmolarity, and elevated inflammatory markers (CRP and ESR), all of which supported an infectious-inflammatory process." (PMID 40901212, 2025). "Laboratory evaluation revealed leukocytosis, anemia, thrombocytosis, and markedly elevated inflammatory markers, including C-reactive protein (CRP) at 98 mg/L and erythrocyte sedimentation rate (ESR) at 57 mm/h." (PMID 41523505, 2025). "Initial laboratory evaluation revealed leukocytosis with neutrophilia (18,200/mm3, 84% neutrophils) and elevated inflammatory markers (CRP 319 mg/L, procalcitonin 2.12 ng/mL)." (PMID 41472238, 2025). "Laboratory results showed elevated LDH (1100 U/L), leukocytosis, increased C-reactive protein (CRP), and hepatic steatosis." (PMID 41174711, 2025). "Initial evaluation at a rural hospital revealed leukocytosis with neutrophilic predominance and an elevated CRP." (PMID 40851708, 2025). "Anemia, leukocytosis and elevated C-reactive protein (CRP) (74.0 mg/L), and Thrombocytopenia were present." (PMID 39857753, 2025). "Repeat laboratory tests confirmed a severe inflammatory response, with increasing leukocytosis and CRP (234.6 mg/L)." (PMID 41440229, 2025). "Patients in the acute phase often present with fever, leukocytosis, elevated C-reactive protein (CRP) levels, and episodic right upper quadrant abdominal pain." (PMID 40535955, 2025). "Laboratory tests results on admission demonstrating leukocytosis, neutrophilia, elevated troponin along with a markedly increased C‐reactive protein (CRP) levels." (PMID 41179610, 2025). "Complete blood count (CBC) showed leukocytosis of 25.9 x 109/L, characterized by 90% neutrophils and 6.3% lymphocytes, along with elevated inflammatory markers, including a C-reactive protein (CRP) of 237 mg/dL and a procalcitonin level of 13.7 ng/mL." (PMID 41306159, 2025). "On the other hand, the patient expressed marked leukocytosis with increased levels of neutrophils, and elevated serum concentration of C-reactive protein (CRP)." (PMID 40370887, 2025). "Laboratory testing revealed mild leukocytosis (10,300/μL; reference range, 4000-10,000/μL) and elevated C-reactive protein (CRP, 0.76 mg/dL; reference range, 0.00-0.30 mg/dL)." (PMID 39944429, 2025). "The typical biochemical features described in RBF include leukocytosis with neutrophilia and a high CRP, while characteristic findings in dengue fever include leukopenia and thrombocytopenia." (PMID 41245666, 2025). "Initial laboratories showed leukocytosis (11,800/cm3), neutrophilia (9,620/cm3), and elevated C-reactive protein (CRP) 69.4 mg/L; urinalysis was positive for leukocyte esterase." (PMID 40761416, 2025). "Laboratory tests showed a C-reactive protein (CRP) at 68 mg/L, leukocytosis (28,800/mm3), lymphocytosis (20,448/mm3), eosinophilia (288/mm3), hemoglobin of 12 g/dL, and thrombocytopenia (88,000/mm3)." (PMID 39802943, 2025). "Laboratory investigations demonstrated leukocytosis (13.4 × 109/L) and a markedly elevated C-reactive protein (CRP, 349 mg/L), reflecting acute infection and systemic inflammation consistent with severe community-acquired pneumonia." (PMID 41328147, 2025).
leukocytosis (continued). "The preoperative blood tests showed persistent leukocytosis (19990/μL) and elevated C-reactive protein levels (28.68 mg/dL), while hemoglobin levels remained normal (13.0 g/dL)." (PMID 40012964, 2025). "Blood cultures collected on the day of admission grew C. coli, and inflammatory markers were elevated, with a C-reactive protein of 8.58 mg/dL and leukocytosis of 11.6 × 109/L with neutrophilia (9.93 × 109/L)." (PMID 41480435, 2025). "Initial features—including systemic inflammation (fever, leukocytosis 11.92 × 109/L, CRP > 200 mg/L), lobar consolidation on imaging, and rapidly progressive pleural effusions—are hallmarks of bacterial pathogens such as S. pneumoniae or K. pneumoniae." (PMID 41488077, 2025). "Laboratory findings indicated that GIS involvement was more common in patients with leukocytosis and elevated CRP levels, suggesting a systemic inflammatory response in these patients." (PMID 40310537, 2025). "Laboratory evaluation demonstrated mild leukocytosis with neutrophilia, along with elevated liver enzymes, lactate, and C-reactive protein levels, similar to findings before the first treatment." (PMID 41472144, 2025). "The main laboratory findings for JSF include leukocytosis or leukopenia, thrombocytopenia, decreased eosinophils, elevated C-reactive protein (CRP), and raised liver enzymes." (PMID 40756773, 2025). "On July 12, 2024, laboratory tests revealed leukocytosis (white blood cell count 16.0 × 109/L), anemia (hemoglobin 98.0 g/L), and markedly elevated inflammatory markers (C-reactive protein 83.0 mg/dL; procalcitonin 96.9 ng/mL)." (PMID 40893890, 2025). "Common laboratory changes observed in pregnant women included lymphopenia, leukocytosis, thrombocytopenia, and increased levels of C-reactive protein, D-dimer, ALT, AST, creatinine, and procalcitonin." (PMID 40218250, 2025). "Laboratory tests revealed inflammatory markers such as leukocytosis (white blood cells = 14.8 × 103/ul) with neutrophilia (neutrophils = 82%), lymphopenia (lymphocytes =12%), and elevated C-reactive protein (CRP = 87 mg/dl)." (PMID 39897744, 2025). "On postoperative day (POD) 6, the patient developed a fever of 38.5°C, elevated inflammatory markers including leukocytosis and C-reactive protein, and pyuria." (PMID 40688940, 2025). "The dynamic laboratory profile supports the clinical course, with an initial systemic inflammatory response syndrome (SIRS) pattern characterized by leukocytosis and markedly elevated C-reactive protein levels." (PMID 40535361, 2025). "Laboratory tests showed slight leukocytosis and elevated C-reactive protein, indicative of systemic inflammation." (PMID 40062037, 2025). "Upon arrival, his laboratory examinations showed leukocytosis, increased inflammatory markers (C-reactive protein (CRP) and procalcitonin (PCT)), and impaired renal function." (PMID 40761967, 2025). "Laboratory findings showed leukocytosis, elevated erythrocyte sedimentation rate, and elevated C-reactive protein, and both blood and thrombus cultures were positive for Streptococcus anginosus." (PMID 40556988, 2025). "Laboratory markers that guide the diagnosis of a diverticular perforation are leukocytosis above 10 x 103/μL and a CRP value over 150 mg/L." (PMID 40926941, 2025). "The results highlight significant leukocytosis, thrombocytosis, and anemia, along with elevated inflammatory markers such as C-reactive protein (CRP)." (PMID 40062024, 2025). "Common indicators of this early response include leukocytosis, C-reactive protein (CRP), and interleukin-6 (IL-6) providing rapid defense against viral intrusion." (PMID 40076968, 2025). "Laboratory tests showed leukocytosis (white blood cell count: 16.8 k/uL, normal range: 3.5-11.3 k/uL) and elevated C-reactive protein (CRP) (148 mg/dL, normal range: 0.0-5.0 mg/dL)." (PMID 40291279, 2025). "Reported laboratory tests revealed leukocytosis in 67.1% of cases, anemia in 37.0% of cases, and elevated C-reactive protein in 91.0% of cases." (PMID 40364971, 2025).
leukocytosis (continued). "Laboratory tests revealed leukocytosis (11 ×109/L), C-reactive protein (CRP) (54 mg/L), and normal renal and liver function." (PMID 41425677, 2025). "Laboratory test results (obtained two hours later) showed elevated troponin (0.04 ng/mL at 0 h → peak 5 ng/mL at 6 h → 1.8 ng/mL at 24 h) and leukocytosis, while C-reactive protein (CRP) and hemoglobin levels were within normal limits." (PMID 40636625, 2025). "Laboratory results revealed mild leukocytosis (13,680/μL; neutrophils 74.6 %, eosinophils 2.6 %) and elevated C-reactive protein (CRP) levels (1.69 mg/dL)." (PMID 39839658, 2025). "Blood tests showed leukocytosis up to 37,800/mm3,elevation of erythrocytes up to 72 mm/h and C-reactive protein (CRP), increase intransaminases, lactate dehydrogenase, blood urea nitrogen (BUN) and creatinephosphokinase (CPK) up to 386 IU/L." (PMID 40351682, 2025). "Leukocytosis was observed in 113 (48%) patients (predominantly neutrophils), and elevated C-reactive protein levels were noted in 120 (51%) patients, representing the most common laboratory findings." (PMID 40656413, 2025). "Other biological abnormalities included elevated CRP in all patients, leukocytosis with a predominance of neutrophils in 11 patients (n = 11, 73.3%), and hyponatremia in seven patients (n = 7, 46.6%)." (PMID 40955254, 2025). "Laboratory evaluation revealed leukocytosis (16,800/μL; reference range: 3,300-8,600/μL) with neutrophil predominance (89.9%; reference range: 40.0-75.0%) and elevated CRP (7.99 mg/dL)." (PMID 41450394, 2025). "In this case, the evaluation revealed systemic inflammatory response syndrome (SIRS), as evidenced by leukocytosis and elevated C-reactive protein and procalcitonin levels, albeit with normal liver function." (PMID 39963623, 2025). "Complete blood count revealed leukocytosis with neutrophilia, and a high-sensitivity C-reactive protein (hs-CRP) exceeding 30 mg/L." (PMID 41515543, 2025). "On 11 March 2025, laboratory tests showed worsening leukocytosis (19.92 × 109/L), persistently elevated CRP (202 mg/L), and hypoalbuminemia." (PMID 41440229, 2025). "Positive correlations between CXCL16 and CRP, leukocytosis, neutrophils, and NLR were confirmed (0.67; 0.46; 0.48; 0.54, respectively)." (PMID 41373861, 2025). "The results revealed marked leukocytosis with neutrophilia and markedly elevated C-reactive protein (CRP), consistent with acute bacterial infection." (PMID 41404206, 2025). "Laboratory results demonstrated a C-reactive protein (CRP) level of 32.7 mg/L and a moderate leukocytosis of 11,400 cells/mm3." (PMID 41393563, 2025). "Laboratory tests of LD patients have revealed leukocytosis with relative lymphopenia and elevated C-reactive protein (CRP) and calcitoninogen levels." (PMID 39975683, 2025). "Regarding laboratory findings, leukocytosis and elevated CRP levels were detected in only 28.6% of cases, indicating a mild or delayed systemic inflammatory response." (PMID 40898255, 2025). "Laboratory tests showed leukocytosis at 19,800/μL (reference range: 5,500-15,500/μL) with a predominance of neutrophils and a markedly elevated CRP level at 12.17 mg/dL (reference range: <0.15 mg/dL)." (PMID 40104470, 2025). "Investigations performed revealed leukocytosis (19,000/mm3) with neutrophilia (14,600/mm3), acute inflammatory syndrome (CRP = 0.9 mg/dL) and an increased value of LDH (277 mg/dL) without hepatic or muscle cytolysis." (PMID 40126322, 2025). "Laboratory tests revealed an inflammatory syndrome, with a C-reactive protein (CRP) level of 89 mg/L (normal range: <10 mg/L) and leukocytosis of 15,800/mm3 (normal range: 4,000-11,000/mm3)." (PMID 40385822, 2025). "Laboratory tests revealed anemia, leukocytosis, elevated C-reactive protein and erythrocyte sedimentation rate, and hypoalbuminemia." (PMID 40611267, 2025).
leukocytosis (continued). "Among physical examination findings, the heel drop test showed diagnostic performance comparable to cough/percussion/hopping tenderness and demonstrated higher sensitivity than laboratory parameters such as leukocytosis, neutrophilia, and elevated CRP levels." (PMID 41473919, 2025). "Lab tests are inconclusive for differentiating mandibular osteomyelitis (MO) from VOC, as both can present with leukocytosis and elevated inflammatory markers (CRP and ESR)." (PMID 40823102, 2025). "Laboratory investigations revealed leukocytosis, neutrophilia, and elevated levels of C-reactive protein (CRP), erythrocyte sedimentation rate (ESR), procalcitonin (PCT), and TNF-α." (PMID 40698081, 2025). "Laboratory studies revealed leukocytosis (21,500 cells/μL) and elevated C-reactive protein (CRP) (14.6 mg/dL)." (PMID 41552223, 2025). "Blood examination revealed leukocytosis (25,940/μL; neutrophils, 88.9%; lymphocytes, 8.0%; eosinophils, 0.5%), hypoproteinemia (total protein, 4.5 g/dL; albumin, 1.6 g/dL), and elevated C-reactive protein (CRP) (21.31 mg/dL) and ferritin (458.7 ng/mL) levels." (PMID 41322776, 2025). "Laboratory investigations revealed leukocytosis, elevated C-reactive protein (CRP), and evidence of coagulopathy, all suggestive of a systemic inflammatory response and evolving complications associated with envenomation." (PMID 41303165, 2025). "Initial laboratory investigations demonstrated leukocytosis with neutrophilia and a significantly elevated C-reactive protein." (PMID 41200654, 2025). "Preoperative labs showed mild leukocytosis, neutrophilia, elevated CRP and fibrinogen, normal procalcitonin and AT, slightly increased coagulation markers, and elevated D‐dimer." (PMID 40534446, 2025). "The nonspecific immunological response was gauged using interleukin 6, leukocytosis, and C-reactive protein." (PMID 40076968, 2025). "Laboratory investigations revealed leukocytosis, markedly elevated CRP, hyponatremia, and impaired renal function, which are consistent with Legionella infection but remain non-specific." (PMID 41328147, 2025). "Biological work-up revealed leukocytosis at 16,440/mm3 and an elevated C-reactive protein (CRP) level of 109 mg/L." (PMID 41170215, 2025). "Laboratory data included leukocytosis, anemia, thrombocytosis, elevated C-reactive protein (CRP), and lactate dehydrogenase (LDH) elevation." (PMID 40862043, 2025). "The laboratory tests revealed leukocytosis, neutrophilia, and elevated C-reactive protein (CRP) levels, consistent with a bacterial infection secondary to the stingray injury." (PMID 40130256, 2025). "Laboratory analyses highlighted a generalized inflammatory state, characterized by leukocytosis with neutrophilia, thrombocytosis, and increased serum C-reactive protein (CRP), which made him unfit for chemotherapy." (PMID 41190326, 2025). "On readmission, laboratory tests showed persistent thrombocytopenia, leukocytosis, neutrophilia, elevated C-reactive protein, and hyponatremia." (PMID 40407649, 2025). "We report a 75-year-old male with cirrhosis presenting with fever (38.2°C), progressive ascites, leukocytosis (109.9×109/L), and elevated CRP (247.41 mg/L)." (PMID 40438677, 2025). "The presence of inflammatory markers (raised ERS, CRP, leukocytosis) and autoimmune markers (ANA Golgi-type/AC-22* +), anti-U1RNP antibodies) suggests an increased risk of ischemia." (PMID 40416235, 2025). "Blood laboratory analysis usually reveals leukocytosis (80–89.7%), elevated C-reactive protein (90.9%), and liver enzyme levels (69–71.6% of cases)." (PMID 40710859, 2025). "Laboratory findings indicated a severe inflammatory response (CRP: 312 mg/L; leukocytosis: 13,000/mm3)." (PMID 40997626, 2025). "Laboratory tests revealed elevated inflammatory markers, including leukocytosis and increased C-reactive protein levels." (PMID 40688940, 2025). "On admission, the patient was clinically stable with leukocytosis, high serum amylase levels, and high CRP levels." (PMID 40370887, 2025).